SMIM26 (small integral membrane protein 26)
Description:
May play a role in cell viability.
Synonyms: LINC00493; LOC388789
Gene: Protein-coding gene on chromosome 20 (18,567,347 to 18,569,563, forward strand). Ensembl gene ENSG00000232388.
Subcellular location: Mitochondrion outer membrane
Subcellular location (Human Protein Atlas): Nucleoplasm; Cytosol
Gene Ontology:
Molecular function: protein binding; protein kinase binding; transmembrane transporter binding
Cellular component: mitochondrial outer membrane; mitochondrion
Homologues: Orthologues: pig SMIM26 (58% identical), dog SMIM26 (49% identical), rat Smim26 (49% identical), mouse Smim26 (47% identical).
Diseases named in the same sentence as SMIM26 in open-access papers:
SMIM26 is named in the same sentence as 5 diseases in open-access papers, as found by Europe PMC text mining. Sharing a sentence is not in itself a finding about the gene and the disease. The quoted sentences say what the papers report.
clear cell renal cell carcinoma (1 paper, 2025). "An intriguing example is SMIM26, a microprotein encoded by the lncRNA LINC00493, which exerts an anti-metastatic function in clear cell renal cell carcinoma (ccRCC)." (PMID 40403492, 2025).
SMIM26 also shares sentences with these, for which no sentence is quoted: tumor (3 papers); colon cancer (1); glioblastoma (1); hepatocellular carcinoma (1).